DDX51 (DEAD-box helicase 51)
Description:
ATP-binding RNA helicase involved in the biogenesis of 60S ribosomal subunits.
Tractability: PROTAC: ubiquitination databases record sites on it; its protein half-life has been measured.
Gene: Protein-coding gene on chromosome 12 (132,136,591 to 132,144,335, reverse strand). Ensembl gene ENSG00000185163.
Subcellular location: Nucleus, nucleolus
Subcellular location (Human Protein Atlas): Nucleoli; Nucleoplasm; Cytosol
Gene Ontology:
Molecular function: RNA binding; ATP binding; ATP hydrolysis activity; nucleic acid binding; RNA helicase activity
Cellular component: membrane; nucleus; nucleolus
Genetic constraint (gnomAD): Loss-of-function variants: 73 observed, 70.11 expected, observed/expected ratio (o/e) 1.04, 90% interval 0.86 to 1.26. The synonymous counts are far from expectation, so gnomAD's model fits this gene poorly and the ratio says little. Missense variants: 1,056 observed, 825.3 expected, observed/expected ratio (o/e) 1.28, 90% interval 1.22 to 1.35. Synonymous variants: 545 observed, 359.14 expected, observed/expected ratio (o/e) 1.52, 90% interval 1.41 to 1.63.
Homologues: Orthologues: chimpanzee DDX51 (97% identical), macaque DDX51 (91% identical), guinea pig DDX51 (78% identical), mouse Ddx51 (75% identical), rat Ddx51 (75% identical), pig DDX51 (74% identical), dog DDX51 (74% identical), tropical clawed frog ddx51 (52% identical), zebrafish ddx51 (48% identical), Drosophila melanogaster Dbp73D (35% identical), Caenorhabditis elegans ZK686.2 (23% identical). Paralogues in human: DDX31 (21% identical), DDX18 (21% identical), DDX42 (20% identical), DDX27 (20% identical), DDX24 (20% identical), DDX43 (20% identical), DDX46 (19% identical), DDX49 (19% identical), DDX17 (19% identical), DDX41 (19% identical), DDX3X (19% identical), DDX3Y (19% identical), and 26 more.
Diseases named in the same sentence as DDX51 in open-access papers:
DDX51 is named in the same sentence as 5 diseases in open-access papers, as found by Europe PMC text mining. Sharing a sentence is not in itself a finding about the gene and the disease. The quoted sentences say what the papers report.
lung carcinoma (1 paper, 2016). "Although DEAD-box RNA helicases are known to play a role in cancer development, including lung cancer, the potential involvement of the novel family member DDX51 has not yet been investigated." (PMID 27198888, 2016).
non-small cell lung carcinoma (1 paper, 2018). A group of at least three distinct histological types of lung cancer, including non-small cell squamous cell carcinoma, adenocarcinoma, and large cell carcinoma. "DDX51 controls non-small cell lung cancer proliferation by regulating cell cycle progression via multiple pathways." (PMID 29373522, 2018).
cancer (5 papers, 2016 to 2024). A tumor composed of atypical neoplastic, often pleomorphic cells that invade other tissues. "Five mutated gene variants that were transferred to the BRCA1-KO fibroblasts (BTN3A2, DDX51, LARP6, AP1G1 and COL18A1) were found to be also present as RNA variants following RNA sequencing of BRCA1-KO fibroblasts after exposure to cancer EVs." (PMID 31200749, 2019). "Meanwhile, the three identified PCGs—DDX51, SPAG17, and NUMA1—have been well studied for their associations with cancers." (PMID 29373522, 2018). "In conclusion, the current results confirmed the importance of the DDX family and pre-rRNA processing in the proliferation of cancer cells, and revealed a role for DDX51 in this process for the first time." (PMID 27198888, 2016). "DDX51 was overexpressed in cancer tissues compared with neighbouring regions (P < 0.05; paired sample test) according to both qRT-PCR and immunohistochemistry." (PMID 27198888, 2016). "Overall, our data suggest for the first time that DDX51 aids cell cancer proliferation by regulating multiple signalling pathways, and that this protein might be a therapeutic target for NSCLC." (PMID 27198888, 2016). "Other family members such as DDX51, DDX5, and DDX53 play important roles in several cancers." (PMID 38807916, 2024). "Consistent with this, our data suggested that DDX51 expression was significantly higher in cancer tissues compared with non-tumour control tissues." (PMID 27198888, 2016).
tumor (2 papers, 2016 to 2023). "While the current data indicate that inhibiting DDX51 expression reduced the proliferation of tumours, future studies will have to address whether the dysregulated expression of DDX51 alone is sufficient to induce uncontrolled cell replication." (PMID 27198888, 2016).
DDX51 also shares sentences with these, for which no sentence is quoted: lung adenocarcinoma (1 paper).